PRADC1 (protease associated domain containing 1)
Description:
Plays a role in the modulation of physical activity and adiposity.
Synonyms: hPAP21; C2orf7; PAP21; MGC13004
Tractability: Antibody: UniProt places it where antibodies can reach, with high confidence; its Gene Ontology location is reachable by antibodies, with high confidence; UniProt predicts a signal peptide or a membrane-spanning region. PROTAC: ubiquitination databases record sites on it.
Gene: Protein-coding gene on chromosome 2 (73,228,010 to 73,233,239, reverse strand). Ensembl gene ENSG00000135617.
Subcellular location: Secreted
Gene Ontology:
Molecular function: protein binding
Cellular component: extracellular region
Genetic constraint (gnomAD): Loss-of-function variants: 17 observed, 15.98 expected, observed/expected ratio (o/e) 1.06, 90% interval 0.73 to 1.59. The upper end of that interval is the gene's LOEUF score, 1.59, which puts it in group 6 of 6, group 1 being the genes least tolerant of losing a copy. Missense variants: 192 observed, 214.53 expected, observed/expected ratio (o/e) 0.89, 90% interval 0.8 to 1.01. Synonymous variants: 65 observed, 84.64 expected, observed/expected ratio (o/e) 0.77, 90% interval 0.63 to 0.94.
Homologues: Orthologues: chimpanzee PRADC1 (100% identical), macaque PRADC1 (100% identical), dog PRADC1 (98% identical), guinea pig PRADC1 (98% identical), pig PRADC1 (98% identical), rabbit PRADC1 (98% identical), mouse Pradc1 (98% identical), rat Pradc1 (98% identical), tropical clawed frog pradc1 (74% identical), Drosophila melanogaster CG9849 (36% identical), Caenorhabditis elegans T07F12.2 (25% identical).
Diseases named in the same sentence as PRADC1 in open-access papers:
PRADC1 is named in the same sentence as 3 diseases in open-access papers, as found by Europe PMC text mining. Sharing a sentence is not in itself a finding about the gene and the disease. The quoted sentences say what the papers report.
melanoma (1 paper, 2020). A malignant, usually aggressive tumor composed of atypical, neoplastic melanocytes. "The gray scale quantification of these images showed that the expression of FKBP4 and RCC1 was significantly upregulated in melanoma, while the expression of PRADC1 was slightly upregulated, and the expression of GBP1 was downregulated (P < 0.05)." (PMID 33194692, 2020). "The expression of GBP1 decreased with the increase of tumor depth (P < 0.0001), and the expression of PRADC1 was the highest in thick melanoma subgroup (P = 0.037)." (PMID 33194692, 2020). "These 13 mRNAs were further analyzed by multivariate COX proportional hazard regression analysis, and finally, four hub mRNAs that could be used to predict melanoma prognosis were selected: PRADC1, FKBP4, RCC1, and GBP1." (PMID 33194692, 2020).
PRADC1 also shares sentences with these, for which no sentence is quoted: cancer (2 papers); tumor (1).